SIRT5 (sirtuin 5)
Diseases named in the same sentence as SIRT5 in open-access papers (continued):
Sharing a sentence is not in itself a finding about the gene and the disease.
tumor (continued). "However, higher levels of nuclear SIRT5 were shown to be associated with tumours <30mm in size (p = 0.038) and the presence of vascular and lymphatic invasion (p = 0.042 & p = 0.033, respectively)." (PMID 26121130, 2015). "Notably, we uncovered a profound association between SIRT5 expression and the molecular pathways governing neuroplasticity, suggesting a novel avenue for future research into the interplay between SIRT5 and the tumor microenvironment." (PMID 39201811, 2024). "The role of SIRT5-mediated desuccinylation in tumor progression underscores its potential as a therapeutic target for cancer treatment." (PMID 39944690, 2025). "In cancer, SIRT5 exhibits a dual role, acting as a tumor promoter or suppressor depending on the context." (PMID 40710366, 2025). "Specifically, we focus on the role of succinylation modification mediated by SIRT5 in tumor progression, highlighting how desuccinylation by SIRT5 modulates tumor development and delineating the underlying mechanisms involved." (PMID 39944690, 2025). "This highlights the cell type- and context-dependent duality of SIRT5, which promotes anti-tumor immunity in certain contexts and immune evasion in others." (PMID 41425553, 2025). "Future studies should focus on dissecting the molecular pathways by which PCED1A influences the SIRT5–succinylation axis and determining its broader impact on mitochondrial function and tumor metabolic adaptation." (PMID 40463370, 2025). "The research on the regulation of specific substrates by different enzymatic activities of SIRT5 in related diseases are summarized in detail as follows, including the dual role of SIRT5 in tumor." (PMID 39979670, 2025). "Increased ROS caused by defective mitochondrial clearance leads to cytotoxicity, demonstrating the anti-tumor activity of SIRT5-autophagy and redox regulation." (PMID 41425553, 2025). "NAD+ and glutamine are important for tumor cells and regulate the metabolism of tumor cells by modulating the activity of SIRT5." (PMID 40865948, 2025). "SIRT5, functioning primarily as a desuccinylase, exhibits significant regulatory roles in tumor biology." (PMID 39944690, 2025). "Silencing SIRT5 in gastric cancer cell lines increased the rate of cell proliferation, migration, invasion, and tumor formation in immunodeficient mice." (PMID 41304967, 2025). "By modulating the succinylation status of key metabolic enzymes and interacting with tumor suppressor pathways, SIRT5 exerts multifaceted influences on tumorigenesis." (PMID 39944690, 2025). "By modulating the expression of different target genes, SIRT5 can either inhibit or promote tumor development." (PMID 39944690, 2025). "Although many articles have proved that SIRT5 desuccinylation can promote tumor growth, there are studies indicating that it can inhibit tumor growth." (PMID 39979670, 2025). "Given the contrasting oncogenic and tumor-suppressive effects of SIRT5, it is evident that the specific role of SIRT5 depends on its key target genes and the type of tumor." (PMID 39944690, 2025). "Conversely, knockout of CDK2 can inhibit malignant proliferation and aerobic glycolysis of cancer cells by increasing SIRT5 expression, revealing a novel role for SIRT5 as a tumor suppressor regulated by upstream genes in cancer." (PMID 39944690, 2025). "SIRT5 tumor promoting activity is mediated by its substrates involved in metabolic regulation, including serine hydroxy methyltransferase 2 (SHMT2)." (PMID 39215785, 2025). "SIRT5 deficiency leads to excessive succinylation of PKM2, which increases IL-1β production, thereby altering the polarization of tumor-associated macrophages (TAMs) and fostering an immunosuppressive environment." (PMID 40463370, 2025). "The deacetylation of K369 on GOT1 by SIRT5 downregulates its activity, inhibits glutamine and glutathione metabolism, and exhibits anti-tumor effects on PDAC cells." (PMID 39979670, 2025).
tumor (continued). "An optimized strategy is called for: the selective activation of protective SIRTs in regular tissue and the blocking of tumor-stimulatory ones, such as SIRT5, would make one more sensitive to chemotherapy." (PMID 41425553, 2025). "Specifically, it seeks to elucidate the role of SIRT5-mediated succinylation modification in tumors, thereby establishing a theoretical foundation for understanding the mechanisms of tumor development." (PMID 39944690, 2025). "Apart from pharmacological interventions, recent studies have identified upstream regulatory genes involved in tumor progression that affect SIRT5 expression." (PMID 39944690, 2025). "Future studies should focus on delineating the precise mechanisms by which SIRT5 exerts its effects, considering the complex interplay between SIRT5 activity, metabolic alterations, and tumor progression." (PMID 39944690, 2025). "As an important desuccinylase, SIRT5 not only promotes tumor proliferation and metastasis, but also inhibits the growth and apoptosis of cancer cells." (PMID 39979670, 2025). "Future studies should focus on elucidating these mechanisms, potentially utilizing advanced genomic and proteomic approaches to comprehensively map SIRT5 interactions within the tumor microenvironment." (PMID 39944690, 2025). "SIRT5 modulates the succinylation status of various target proteins and exhibits complex roles across different tumor types." (PMID 40463370, 2025). "In line with this, SIRT5 knockout or expression of succinylation mimicking mutant of SHMT2 (K280E) led to the suppression of tumor development in vitro and in vivo." (PMID 39215785, 2025). "SIRT5 plays a tumor suppressor role in head and neck squamous cell carcinoma, glioma, endometrial carcinoma, PDAC,173 and gastric cancer." (PMID 39215785, 2025). "Further analysis revealed that SLC25A51 activates SIRT5 expression, promoting a metabolic shift from oxidative phosphorylation to glycolysis—a key mechanism driving tumor progression." (PMID 39944690, 2025). "SIRT5 serves as a tumor suppressor by inhibiting cancer cell proliferation and metastasis, enhancing resistance to ROS, and inhibiting the Warburg effect." (PMID 41304967, 2025). "SIRT5 is not only involved in physiological metabolism, but also in tumor regulation and immunomodulation." (PMID 39979670, 2025). "A primary challenge is the need for a deeper understanding of the molecular mechanisms by which SIRT5 exerts its effects on tumor biology." (PMID 39944690, 2025). "Ectopically expressed SIRT5 partially mimicked the therapeutic effect of histidine therapy, implying a tumor-suppressing capacity of SIRT5 in B-ALL." (PMID 38485947, 2024). "The tumor size, weight and volume were suppressed in the sh-SIRT5 group compared with that in the sh-NC group." (PMID 38532359, 2024). "SIRT5 is an important tumor regulator because of its potent deacetylase, desuccinylase, deglutarylase, and demalonylase activities." (PMID 38485947, 2024). "In mouse models, the genetic ablation of Sirt5 promotes acinar-to-ductal metaplasia, precursor lesion formation and heightened tumor growth, correlating with poor survival outcomes." (PMID 39682281, 2024). "SIRT5 exhibits context-dependent dual effects in cancers by acting as either a tumor suppressor or an oncogenic factor." (PMID 39201811, 2024). "The RT-qPCR and Western blot results indicated that the mRNA and protein levels of SIRT5 were increased in tumor tissues in comparison with the normal ones." (PMID 38532359, 2024). "Acting as both a metabolic regulator and a suppressor of tumor growth and spread, SIRT5 plays a crucial role in modulating key oncogenic signaling pathways, making it a vital player in the metabolic and molecular landscape of PCa." (PMID 39796040, 2024). "The results reveal an increase in SIRT5 protein expression within the Tumor group compared to the Normal group." (PMID 39110260, 2024).
tumor (continued). "The varied roles of SIRT3, SIRT4, and SIRT5 in metabolic adaptation and cancer are outlined, emphasizing their tumor suppressor or oncogenic nature." (PMID 38331199, 2024). "This tumor-specific metabolic vulnerability underscores the potential therapeutic application of targeting SIRT5 in CRC." (PMID 38773972, 2024). "Collectively, these results suggest that SIRT5 functions as a tumor suppressor in GBM, and its loss of function promotes GBM cell proliferation in vitro and tumor growth in vivo." (PMID 39201811, 2024). "By contrast, associations of dasatinib sensitivity with stronger upregulation of SIRT1, SIRT2, and SIRT5 were unexpected, since these genes have tumour promoting effects, and their downregulation positively affects cancer treatment outcomes." (PMID 38369747, 2024). "The results showed that the protein expression of SIRT5 was significantly lower in tumor tissue compared to normal tissue and was negatively related to the age of the patient ccRCC individual tumor stages, and grades." (PMID 37096064, 2023). "The accumulation of primary bile acid TCA in the liver creates an immunosuppressive tumor microenvironment controlled by the metabolic regulatory gene Sirt5." (PMID 38169837, 2023). "Yang and colleagues found in a recent study that serine hydroxymethyltransferase 2 (SHMT2) desuccinylation on Lys280 by SIRT5 leads to an increase in its enzymatic activity and tumor cell proliferation." (PMID 36980194, 2023). "In this setting, by controlling the NRF2/HO-1 pathway, which contributes to raising GSH levels, SIRT5 confers resistance to genotoxic chemotherapeutics such as cisplatin, thereby supporting tumor growth." (PMID 36980194, 2023). "SIRT5 was also found overexpressed in cultured SH-EP neuroblastoma cells and protected them from apoptosis by lowering ROS levels, thereby exerting a tumor promoting action." (PMID 36980194, 2023). "Like other SIRTs, SIRT5 has a double-faced role in cancer, acting as either a tumor promoter or suppressor not only in different types of tumors but also in the same ones under different experimental settings." (PMID 36980194, 2023). "The potential of SIRT5 to promote the survival of tumor cells by lowering oxidative stress and maintaining glutamine catabolism and oxidative phosphorylation is linked to its tumor-promoter action." (PMID 36980194, 2023). "SIRT5 also exhibits a tumor suppressor behavior in a variety of cancer types by interfering with several pathways." (PMID 36980194, 2023). "Recently it has been suggested that tumour cells exploit SIRT5-mediated regulatory mechanisms as tumour inducer, however, the expression and effect of SIRT5 is highly varied depending on the tissue context." (PMID 38213532, 2023). "The protein expression of SIRT5 was significantly lower in tumor tissue compared to normal tissue and was negatively related to the age of the patient ccRCC individual tumor stages, and grades." (PMID 37096064, 2023). "The interaction of rCsNOSIP with ASPSCR-1 and Sirt-5, two screened proteins closely related to tumor progression, was confirmed by GST-pull down assay." (PMID 37948465, 2023). "SIRT5 also seems to function as a tumor suppressor in HCC and its expression was found to be reduced in primary liver cancer tissues compared with healthy liver tissues." (PMID 36980194, 2023). "In human ccRCC samples, strong IHC staining expression of SIRT5 was displayed in adjacent normal tissue than in tumor tissues." (PMID 37096064, 2023). "Sirtuins, a family of orthologues of yeast silent information regulator 3 (SIRT3), 4 (SIRT4) and 5 (SIRT5) are important tumor suppressor genes located in mitochondria." (PMID 36809279, 2023). "Tumour cells can for example promote an antioxidant response through enhanced SIRT5-mediated protein desuccinylation to avoid ROS-induced apoptosis." (PMID 38213532, 2023). "While Sirt3 and Sirt4 have been identified as tumor suppressors, Sirt5 has been reported to be a tumor promoter in various types of cancer." (PMID 35963851, 2022).
tumor (continued). "The decreased expression levels of SIRT2, SIRT4, and SIRT5 were correlated with advanced tumor stages." (PMID 35136826, 2022). "Targeted metabolomics analysis of tumor lysates revealed that SIRT5 overexpression increased the amount of R5P and nucleotides." (PMID 36253417, 2022). "In the next sections, we reportdifferent cases in which SIRT5 exhibits either a tumor-suppressoror tumor-promoter function." (PMID 35802779, 2022). "For example, SIRT5 can also act as a tumor suppressor to promote tumor cell apoptosis via its desuccinylase activity." (PMID 36060706, 2022). "Consistent with our in vitro results, targeted metabolomics analysis of tumor lysates revealed that SIRT5 silencing resulted in a significant downregulation in the levels of R5P and nucleotides." (PMID 36253417, 2022). "As demonstrated by in vitro and in vivo experiments, SIRT5 exerts tumor suppressor functions in glioma,where its desuccinylase activity plays pivotal roles in maintainingmitochondrial functions and arresting cell proliferation." (PMID 35802779, 2022). "To study the role of the SIRT5–TKT axis on tumor behavior in vivo, we generated a surgical orthotopic mouse model by injecting luciferase-transfected HCT116 cells stably expressing NTC shRNA or SIRT5 shRNAs into the cecum of nude mice." (PMID 36253417, 2022). "Although SIRT5 has sometimes been shown to be tumor-promoting, several studies have shown a tumor suppressor function." (PMID 36230997, 2022). "Current research supports the role of SIRT5 as a tumor suppressor in many cancers, and this effect is achieved by regulating metabolism-related pathways." (PMID 36568393, 2022). "In contrast, Xiangyun and co-workers reported that SIRT5 desuccinylates PKM2 at Lys498 to inhibit its activity in tumor cells." (PMID 35889322, 2022). "This led to the discovery that the inhibition of SIRT5 or the use of the succinic mimic mutant PKM2(K498E) can inhibit tumor cell proliferation." (PMID 36359005, 2022). "We found that in comparison with the control group, both tumor volume and weight in the SIRT5-silencing group were significantly restrained." (PMID 36253417, 2022). "The animal study showed that the tumor size of the SIRT5-KD group was significantly larger than that of the control group." (PMID 34930316, 2021). "Regarding the expression patterns of Sirt5 in cancer, it has been demonstrated that Sirt5 mRNA expression tends to be elevated in tumor tissues compared with the corresponding normal tissues." (PMID 33455080, 2021). "Our results showed that expression of CPT1A or SIRT5 was negatively correlated with deeper tumor infiltration and distant metastasis, whereas the expression of SIRT7 exhibited opposite effect." (PMID 33681201, 2021). "We further detected the expression of SIRT5 in 72 paired ccRCC tumor samples obtained from Ruijin Hospital and found that SIRT5 expression was significantly decreased in the tumor samples compared with paracancerous normal tissues (P = 4.117e−09)." (PMID 34930316, 2021). "SIRT5 was expressed at low levels in tumor tissues, and levels of PHDA1 succinylated at K351 were observed in ccRCC samples." (PMID 34930316, 2021). "In the A2058 melanoma tumor xenograft model, SIRT5 depletion significantly delayed the tumor growth." (PMID 34650436, 2021). "The results of our study showed that SIRT5 functioned as a tumor suppressor in ccRCC and correlated with metabolic reprogramming during tumor growth and metastasis by regulating the hyposuccinylation of PHDA1." (PMID 34930316, 2021). "The expression level of SIRT5 protein in tumours was markedly higher than that in normal adjacent tissues." (PMID 33103371, 2020). "A review of Shankavaram CellLine (Oncomine) the expression of SIRT5 in PC3 cells is impressive compared to other tumour cell lines." (PMID 33103371, 2020).
tumor (continued). "All the data in vivo illustrated the inhibition of tumour growth and lung metastasis via overexpressed SIRT5." (PMID 32596968, 2020). "A review of the Human Protein Atlas database identified 62 cell lines of various tumours with increased SIRT5 expression." (PMID 33103371, 2020). "Tumor suppression is associated with upregulation of SIRT1 levels, whereas SIRT3 and SIRT5 act differently as tumor promoters." (PMID 31137785, 2019). "Collectively, these in vivo and in vitro results indicated the K329 deacetylation of LDHB by SIRT5 promoted cancer cell proliferation and tumour growth." (PMID 30443978, 2019). "Consistent with our previous in vitro results, IHC analysis of tumours also revealed that GW5074 reduced SIRT5 protein level and resulted in a significant downregulation of autophagic flux and cell proliferation." (PMID 30443978, 2019). "Based on the importance of SIRT5 in tumour progression, we asked which regulatory signalling factors were directly regulated by SIRT5." (PMID 30443978, 2019). "Conversely, we found reduced CRC tumorigenesis, and decreased tumor volume and weight in the SIRT5 knockdown xenograft mice." (PMID 29416026, 2018). "Consistent with our previous in vitro results, GC-MS analysis of tumor lysates also revealed that SIRT5 silencing resulted in a significant downregulation of TCA cycle metabolites, including α-KG, succinate, fumarate, malate, citrate, and isocitrate." (PMID 29416026, 2018). "Another finding of this study is that inhibition of Sirt5 can suppress tumor cell proliferation through desuccinylation of PKM2 K498, which provides a potential target for clinical cancer research and treatment." (PMID 28036303, 2017). "Our data indicate that PKM2 desuccinylation by SIRT5 would provide an advantage for tumor cell growth by allowing them to sustain antioxidant responses and thereby support cell survival and proliferation under acute oxidative stress." (PMID 28036303, 2017). "To further prove SIRT5 mediated desuccinylation of PKM2 is important for tumor cell proliferation, we knocked down Sirt5 in A549 cells and compared the cell proliferation rate with control cells." (PMID 28036303, 2017). "To confirm this finding, we treated a549 cells with SIRT5 inhibitors Suramin and checked its effect on cell proliferation and found that Sirt5 inhibitor also suppressed tumor cell proliferation, indicating Sirt5 is a potential target for lung tumor treatment." (PMID 28036303, 2017). "SIRT5, another mitochondrial sirtuin, appears to act predominantly as a tumor suppressor." (PMID 40710366, 2025). "Additionally, the unique role of SIRT5 in mitochondrial metabolism, particularly in fatty acid oxidation, highlights its significance in cellular energy production and tumor progression." (PMID 39944690, 2025). "In cancer, SIRT5 acts as either a tumor promoter or suppressor in a context‐dependent fashion." (PMID 39215785, 2025). "Consequently, the application of SIRT5 as a therapeutic target necessitates personalized research approaches tailored to specific tumor types and microenvironments." (PMID 39944690, 2025). "At present, many studies have proved that SIRT5 desuccinylation can promote tumor growth." (PMID 39979670, 2025). "Thus, therapies that increase malonylations in tumor cells (via SIRT5 inhibition, MCD inhibition, or the delivery of cell-permeable malonyl-CoA analogs that specifically malonylate certain targets) are being explored as anticancer strategies." (PMID 41107644, 2025). "Understanding how SIRT5 influences immune cell function and tumor-immune interactions may provide insights into novel therapeutic strategies that combine SIRT5 modulation with immunotherapeutic approaches." (PMID 39944690, 2025). "Therefore, modulating SIRT5 expression appears to be an effective means of alleviating tumor progression." (PMID 39944690, 2025).